SORCS3 (sortilin related VPS10 domain containing receptor 3)
Description:
Plays an important role in modulating synaptic transmission and plasticity in the hippocampus, probably by affecting the trafficking and localization ofAMPA-type glutamate receptors in the postsynaptic density.
Synonyms: KIAA1059; SORCS
Tractability: Antibody: UniProt places it where antibodies can reach, with high confidence; its Gene Ontology location is reachable by antibodies, with high confidence; UniProt predicts a signal peptide or a membrane-spanning region. PROTAC: its protein half-life has been measured.
Gene: Protein-coding gene on chromosome 10 (104,641,290 to 105,265,242, forward strand). Ensembl gene ENSG00000156395.
Subcellular location: Cell membrane; Synaptic cell membrane; Postsynaptic density
Subcellular location (Human Protein Atlas): Plasma membrane
Gene Ontology:
Molecular function: protein binding; neuropeptide receptor activity; transmembrane signaling receptor activity
Biological process: neuropeptide signaling pathway; positive regulation of synaptic transmission; regulation of synaptic plasticity; postsynaptic modulation of chemical synaptic transmission
Cellular component: plasma membrane; membrane; postsynaptic density; postsynaptic density membrane; synaptic membrane; glutamatergic synapse
Genetic constraint (gnomAD): Loss-of-function variants: 44 observed, 109.92 expected, observed/expected ratio (o/e) 0.4, 90% interval 0.31 to 0.51. The upper end of that interval is the gene's LOEUF score, 0.51, which puts it in group 2 of 6, group 1 being the genes least tolerant of losing a copy. Missense variants: 1,251 observed, 1,414.8 expected, observed/expected ratio (o/e) 0.88, 90% interval 0.84 to 0.93. Synonymous variants: 622 observed, 555.18 expected, observed/expected ratio (o/e) 1.12, 90% interval 1.05 to 1.2.
Homologues: Orthologues: chimpanzee SORCS3 (99% identical), macaque SORCS3 (97% identical), rabbit SORCS3 (95% identical), mouse Sorcs3 (92% identical), rat Sorcs3 (92% identical), pig SORCS3 (89% identical), dog SORCS3 (87% identical), guinea pig SORCS3 (83% identical), tropical clawed frog sorcs3 (71% identical), zebrafish SORCS3 (53% identical), zebrafish sorcs3b (50% identical). Paralogues in human: SORCS1 (61% identical), SORCS2 (40% identical), SORL1 (22% identical), SORT1 (15% identical).
Diseases named in the same sentence as SORCS3 in open-access papers:
SORCS3 is named in the same sentence as 30 diseases in open-access papers, as found by Europe PMC text mining. Sharing a sentence is not in itself a finding about the gene and the disease. The quoted sentences say what the papers report.
depression (8 papers, 2013 to 2025). "Mouse studies of the murine orthologue of SORCS3 have implicated it in long-term synaptic depression via aberrant glutamate signalling." (PMID 39009701, 2025). "SORCS3 has been associated with major depressive disorder (MDD), bipolar disorder (BPD), schizophrenia (SCZ), attention deficit hyperactivity disorder (ADHD), ASD, dementia in women, neuroticism, educational attainment and intelligence (IQ)." (PMID 36833409, 2023). "STAG1 was associated with autism spectrum disorder, feeling nervous, feeling worry and neuroticism, whereas SORCS3 was associated with Alzheimer, depression, feeling nervous and neuroticism." (PMID 33431988, 2021). "The comparison of our anxiety-related genes with human GWAS for neurological conditions identified Stag1 and Sorcs3 associated with four conditions including “Alzheimer's disease”, “autism spectrum disorder, “depression”, “feeling nervous”, “feeling worry”, and “neuroticism”." (PMID 33431988, 2021). "One study displayed that SORCS3 is also a risk gene for major depressive disorder." (PMID 32304290, 2020). "rs1021362 lies in SORCS3, a gene previously associated with stress response associated with MD, rs3793577 lies in ELAVL2, whose silencing in animal models is associated with reduced behavioral despair; the remaining GVs have been previously associated with major depression by several PheWAS studies." (PMID 35886042, 2022). "Other genes that located outside of the MHC region, such as MAD1L1, RERE, SORCS3 and ANKK1, are associated with neuronal development and guidance of neuronal growth, transcriptional processes and other risk factors for depression, for example, obesity, smoking and abnormal physical development." (PMID 35354486, 2022).
Alzheimer disease (6 papers, 2009 to 2025). A progressive, neurodegenerative disease characterized by loss of function and death of nerve cells in several areas of the brain leading to loss of cognitive function such as memory and language. "In addition, SORCS3 mutations have been linked with intellectual delay, multiple sclerosis and Alzheimer’s disease." (PMID 39009701, 2025). "Genetic variants of SORCS3 are risk factors for Alzheimer disease (AD)." (PMID 35911978, 2022). "Genetic variation in SORCS3 has been associated with Alzheimer’s disease in humans with more recent studies suggesting that additive epistatic effects of genetic variants within the gene may be important." (PMID 30717660, 2019).
schizophrenia (3 papers, 2020 to 2025). A major psychotic disorder characterized by abnormalities in the perception or expression of reality. "SORCS3, the most pleiotropic schizophrenia-associated gene uncovered by these analyses due to its association with two of the other disorders considered, is implicated in a number of neurologically salient processes including modulation of synaptic depression and glutamate receptor functionality." (PMID 32398653, 2020). "SORCS3 has previously been suggested as a pleiotropic gene associated with ADHD, autism, schizophrenia, bipolar, and MDD." (PMID 39009701, 2025). "The SORCS3 gene-set was enriched for heritability contributing to schizophrenia (SCZ), bipolar disorder (BPD), intelligence (IQ) and education attainment (EA)." (PMID 36833409, 2023). "One gene, Sortilin related VPS10 domain containing receptor 3 (SORCS3), was associated with schizophrenia and two of the additional disorders—ADHD and MDD (PSZ = 2.91 × 10−8, PADHD = 1.51 × 10−9, and PMDD = 5.66 × 10−8)." (PMID 32398653, 2020).
attention deficit-hyperactivity disorder (2 papers, 2019 to 2023). A disorder characterized by a marked pattern of inattention and/or hyperactivity-impulsivity that is inconsistent with developmental level and clearly interferes with functioning in at least two settings (e.g. at home and at school). "Furthermore, variation in SORCS3 has been associated with attention deficit hyperactivity disorder and SORCS3 knockout mice display defects in spatial learning and memory, as well as increased fear extinction." (PMID 30717660, 2019).
bipolar disorder (2 papers, 2013 to 2023). A disorder of the brain that causes unusual shifts in mood, energy, activity levels and the ability to carry out day-to-day tasks. "Although highly speculative at present, one genetic study reported a de novo duplication of the chromosomal region 10q23 encoding SORCS1 and SORCS3 in an individual with bipolar disorder." (PMID 24069373, 2013).
diabetes (2 papers, 2017 to 2022). "SORSC1 has been associated with insulin secretion and diabetes risk and loss of both Sorcs1 and Sorcs3 in mutant mice caused increased adiposity and enhanced food intake, but not increased body weight." (PMID 35330733, 2022). "SORCS3 is thought to have a role in type I and II diabetes via an interaction with the insulin-sensitive glucose transporter GLUT4." (PMID 28702049, 2017).
gastric cancer (2 papers, 2021). A primary or metastatic malignant neoplasm involving the stomach. "SORCS3, ZNF154 and ZNF177 are hypermethylated in gastric cancers, while ZNF177 is also hypermethylated in hepatocellular carcinomas." (PMID 34882728, 2021).
multiple sclerosis (2 papers, 2023 to 2025). A progressive autoimmune disorder affecting the central nervous system resulting in demyelination. "In addition, genetic analysis of the isolated Faroe Islands revealed SORCS3 as a potential multiple sclerosis risk gene." (PMID 37554401, 2023).
Obesity (2 papers, 2018 to 2022). Accumulation of substantial excess body fat. "Taken together, ablation of SORCS1 and SORCS3 expressions in mice on a normal chow resulted in a distinct metabolic phenotype with a shift in energy substrate preference, diminished usage of lipids as metabolic fuel, and increased adiposity in the absence of classical obesity manifestation." (PMID 29440124, 2018).
Anxiety (1 paper, 2021). Intense feelings of nervousness, tension, or panic often arise in response to interpersonal stresses. "For example, our study suggests that Sorcs3 regulates anxiety by modulating abundance of Bacteroidaceae." (PMID 33431988, 2021). "The roles of Stag1 and Sorcs3 in anxiety were not reported before, but the human GWAS data and our mice GWAS data imply that there could be a connection between these genes and anxiety." (PMID 33431988, 2021).
Autoimmunity (1 paper, 2023). The occurrence of an immune reaction against the organism's own cells or tissues. "SORCS3 is associated with both autoimmunity and tumors, but the specific pathway regulating SLE pathogenesis, perhaps NGF/p75NTR or other pathways, needs to be further explored." (PMID 37554401, 2023).
diffuse large B-cell lymphoma (1 paper, 2023). "Transcriptomic sequencing in patients with refractory diffuse large B cell lymphoma (DLBCL) showed increased expression of SORCS3." (PMID 37554401, 2023).
dyslexia (1 paper, 2025). A learning disorder characterized by an impairment in processing written words. "Four genes – SORCS3, TCTA, TRAIP and AMT – shown to be pleiotropic had previously been associated with dyslexia and ADHD in individual GWAS studies and are very strong pleiotropic candidate genes." (PMID 39009701, 2025).
glioblastoma (1 paper, 2023). The most malignant astrocytic tumor (WHO grade IV). "SORCS3 is a member of the vacuolar protein sorting 10 protein (VPS10p) receptor family and uses the NGF/p75NTR pathway in glioblastoma (GBM) to suppress cell invasion and proliferation." (PMID 37554401, 2023).
glioma (1 paper, 2022). A benign or malignant brain and spinal cord tumor that arises from glial cells (astrocytes, oligodendrocytes, ependymal cells). "We found that SorCS3-mediated cellular internalization is one of the key mechanisms for suppressing glioma metastasis and proliferation." (PMID 35393432, 2022). ", western blot analysis showed that SorCS3 expression was significantly decreased in the U87 cell line compared to the other glioma cell lines tested." (PMID 35393432, 2022). "In the present study, we revealed a novel molecular mechanism by which SorCS3 promotes internalization to regulate glioma progression." (PMID 35393432, 2022). "Low expression of SorCS3 was closely related to IDH wild-type gliomas, 1p/19q gliomas, and recurrent gliomas." (PMID 35393432, 2022). "However, after NGF treatment, the effect of SorCS3 was amplified in two glioma cell lines (U87 and U251)." (PMID 35393432, 2022). "In addition, we analysed data from the TCGA database and found that the expression of SorCS3 in gliomas is significantly reduced." (PMID 35393432, 2022). "However, we detected the expression of SorCS3 in glioma tissue microarray samples and cell lines." (PMID 35393432, 2022). "Immunofluorescence (IF) and Co-Immunoprecipitation (Co-IP) detection confirmed that SorCS3 bound to p75NTR, which subsequently increased the internalization of p75NTR, and then transported p75NTR to the lysosome for degradation, ultimately contributing to inhibit of glioma progression." (PMID 35393432, 2022). "Taken together, our work suggests that SorCS3 is a marker of promising prognosis in GBM patients and suggests that SorCS3 regulates internalization, which plays a pivotal role in inhibiting glioma progression." (PMID 35393432, 2022). "Although findings from an earlier report indicate that SorCS3 binds NGF and that NGF is an influencing factor of glioma cell progression, the functional implications of these interactions are poorly understood." (PMID 35393432, 2022).
Hyperglycemia (1 paper, 2018). An increased concentration of glucose in the blood. "Though the mutant mice showed a mild impairment in glucose tolerance at young age (12 weeks; Fig EV2B and C), this phenotype did not progress to hyperglycemia during aging (Fig EV3A), suggesting that SORCS1 and SORCS3 are dispensable for glycemic control in chow‐fed mice." (PMID 29440124, 2018).
mental disorder (1 paper, 2022). A disease that has its basis in the disruption of mental process. "The list of pleiotropic risk factors acting across a variety of psychiatric disorders includes such well-described candidates as NEGR1, SOX5, SORCS3, DCC, and TCF4 and indicates that MDD and PTSD are part of the greater spectrum of mental disorders with shared genetic liability." (PMID 33905376, 2022).
polycystic kidney disease (1 paper, 2018). A usually autosomal dominant and less frequently autosomal recessive genetic disorder characterized by the presence of numerous cysts in the kidneys leading to end-stage renal failure. "The members of the SorCS subfamily (SorCS1, SorCS2, and SorCS3) all contain a region rich in leucine residues that consists of a polycystic kidney disease (PKD) domain (pdb-id 1WGO) and an additional 202 residues of unknown fold." (PMID 30061605, 2018).
skin cancer (1 paper, 2015). "Overall, skin cancer had the highest somatic mutation frequencies for genes within cancer susceptibility regions, with SORCS3, CDKN2A, and TRIOBP all having mutations in over 10 % of samples." (PMID 26374197, 2015).
psychiatric disorder (4 papers, 2020 to 2023). A disorder characterized by behavioral and/or psychological abnormalities, often accompanied by physical symptoms. "Studies have identified associations between both rare and common variants of the SORCS3 gene and multiple psychiatric disorders, neurodegenerative disorders and other brain-related disorders and phenotypes." (PMID 36833409, 2023). "Recently, the Psychiatric Genomic Consortium identified SORCS3 as a shared top-risk gene across 8 different psychiatric disorders highlighting the pleiotropic though unclear function of SorCS3 in healthy and diseased human brain." (PMID 36397124, 2022). "This indicates that SORCS3 functions within a network of genes that contribute to psychiatric disorders and behavioural phenotypes." (PMID 36833409, 2023).
tumor (4 papers, 2021 to 2024). "Noteworthy, overexpression of ANKRD6, ITIH3 and SORCS3 was detected in tumor compared with control tissue in the patients presenting poor survival." (PMID 38480611, 2024). "These genes are ANKRD6, ITIH3, SORCS3, NPY1R and CCDC178, which form a signature associated to adverse clinic-pathological features such as advanced tumor stage, poor prognosis and disease recurrence in GC." (PMID 38480611, 2024). "We analysed SorCS3 expression according to grade, with grades I–IV corresponding to well-differentiated to poorly differentiated tumours." (PMID 35393432, 2022). "Taken together, these findings indicated that inhibiting the internalization or the binding between NGF and SorCS3 interfered with the tumour suppressor function of SorCS3." (PMID 35393432, 2022). "In vitro wound healing and Transwell assays demonstrated that overexpression of SorCS3 reduced the migratory and invasive potential of tumour cells." (PMID 35393432, 2022). "In contrast to the driver gene FAM133A, the driver gene SORCS3, in combination with its co-expressed genes, plays an important role in tumor metastasis, hypoxia and apoptosis." (PMID 34567094, 2021). "SorCS3 regulates p75NTR by controlling its internalization from the plasma membrane to the lysosome, thereby limiting signal transduction, an essential driving force of tumour aggressiveness." (PMID 35393432, 2022). "In summary, we concluded that SorCS3 functions as a tumour suppressor gene in GBM cells in vitro." (PMID 35393432, 2022). "Taken together, these data demonstrated that SorCS3 is significantly downregulated in GBM, suggesting that it may function as a tumour suppressor." (PMID 35393432, 2022).
cancer (3 papers, 2015 to 2022). A tumor composed of atypical neoplastic, often pleomorphic cells that invade other tissues. "To further verify that the biological function of SorCS3 in suppressing cancer is achieved through the NGF/p75NTR signalling pathway, we selected the competitive NGF inhibitor Ro 08-2750 to inhibit binding between endogenous NGF and p75NTR." (PMID 35393432, 2022). "Taken together, these results suggested that SorCS3 can weaken the cancer-promoting effect of NGF and that NGF can enhance the SorCS3-regulated internalization of p75NTR." (PMID 35393432, 2022). "In this study, we demonstrate that SorCS3, a sorting protein previously not investigated in carcinomas, is expressed at low levels in GBM cell lines and patients." (PMID 35393432, 2022).
brain diseases (1 paper, 2023). "The SORCS3 gene was proven to be related to the pathophysiology of destructive diseases of the nervous system, leading to the occurrence and development of brain diseases." (PMID 37372363, 2023).
SORCS3 also shares sentences with these, for which no sentence is quoted: amyloidosis (1 paper); autism (1); autism spectrum disorder (1); cognition disorder (1); dementia (1); gastrointestinal tumour (1); hepatocellular carcinoma (1).